IL1A (interleukin 1 alpha)
Diseases named in the same sentence as IL1A in open-access papers (continued):
Sharing a sentence is not in itself a finding about the gene and the disease.
malaria (14 papers, 2011 to 2024). Malaria is a serious and sometimes fatal disease caused by a parasite that commonly infects a certain type of mosquito which feeds on humans. "This study established the role of IL-1α in the liver pathology caused by blood-stage P. chabaudi malaria." (PMID 31110285, 2019). "For instance, the A114S nsSNP in the IL1A gene (GT; dbSNP: rs17561) is predicted to decrease protein stability and has been strongly associated with various types of diseases that affect inflammatory responses, atopy, and infectious diseases, such as malaria." (PMID 38858637, 2024). "Previous studies implicate IL-1α in the pathogenesis of fulminant hepatic failure and endoplasmic reticulum stress-induced liver damage, and for the first time, we demonstrated its role in the liver injury caused by malaria." (PMID 31110285, 2019). "A high incidence of the IL1A gene polymorphism (−4845G > T), which leads to an increased IL-1α production, is described in Vietnamese patients with severe malaria, and high serum levels of IL-1β are also associated with severe disease in individuals from West Africa24,25." (PMID 31110285, 2019). "The implication of IL-1α in liver inflammation and necrosis caused by P. chabaudi infection, as well as in weight loss and hypothermia, opens up new perspectives for improving malaria outcomes by inhibiting IL-1 signaling." (PMID 31110285, 2019). "Interleukin-5, IL-1α, and IL-10 were significantly higher in malaria seropositive than seronegative volunteers." (PMID 38274822, 2023). "To verify the production of IL-1α during hepatic necrosis and inflammation induced by blood-stage malaria, we first evaluated the serum concentration of the liver damage indicators enzymes AST, ALT and LDH." (PMID 31110285, 2019). "Indeed, our results showing the TUNEL+ cells in the liver suggested that the hepatocytes died by apoptosis during acute malaria and this process was amplified by IL-1α." (PMID 31110285, 2019). "TNF-α production in the liver during malaria, which, according to our study, is potentiated by IL-1α, may be directly involved in the death of hepatocytes and the development of necrotic lesions." (PMID 31110285, 2019). "Therefore, P. chabaudi malaria induces NLRP3 inflammasome-independent IL-1α production in the liver." (PMID 31110285, 2019). "In addition, an increase in IL-1α as a consequence of somatic variants, such as the IL1A gene single nucleotide polymorphism (SNP) rs17561, has been implicated in higher risk of severe malaria." (PMID 33672278, 2021). "Previous studies showed overexpression of pro-inflammatory cytokines TNFα, IL-1α and IL-6 in CM patients promotes pathogenesis of CM (acute immune activation, promotion of adhesion molecules, leukocyte recruitment, fever and BBB disruption) and were associated with severe and lethal malaria." (PMID 24433482, 2014). "Analysis of SNPs in the IL22 gene found several weak associations with severe malaria in Gambian children but no clear cut effect while a SNP in IL1A (encoding interleukin1α) and another in IL1B (encoding interleukin-1β) showed a marginal association with susceptibility to malaria." (PMID 24312262, 2013). "When stratified by malaria sero-status, IL-1α (p=0.034), IL-5 (p=0.023) and IL-10 (p=0.024) were significantly higher in malaria sero-positive than sero-negative volunteers." (PMID 38274822, 2023). "One study suggested that the glycosylphosphatidylinositol antigen of malaria induces monocyte and macrophage activation, resulting in the release of proinflammatory cytokines, such as tumor necrosis factor-α (TNF-α) and IL-1α, and the phagocytosis of both infected red blood cells and leukocytes." (PMID 32574170, 2020). "All these biomarkers were lower in the second samples confirming the induction of different types of immune mediators including growth factor (G-CSF), inflammatory (TNFα, IL-1α, IP-10), anti-inflammatory (IL-10) and chemokines (IL-8, MCP-1) during immune response to malaria." (PMID 27168977, 2016).
breast tumors (13 papers, 2004 to 2025). "Expression of S100A7 in breast tumors negatively impacts prognosis through enhancing proliferation, production of proinflammatory molecules (IL-1α, CXC-L1, CXC-L8) and tumor-associated macrophages (TAMs) recruitment." (PMID 39830522, 2024). "Administration of a single dose of these NPs (equivalent to 7.5 μg IL‐1α) i.p. on Day 1 of treatment to breast tumor (TUBO)‐bearing BALB/c mice caused significant tumor regression in 80% of treated mice." (PMID 37206237, 2023). "This study introduced a novel IL-1α-TSLP-mediated crosstalk between breast tumor cells and tumor-infiltrating myeloid cells regulating metastatic breast cancer." (PMID 33430381, 2021). "Our observation of the decreased IL-1α expression in the breast tumors of mCMV-infected MMTV-PyVT mice suggests that mCMV plays a role in immune regulation and affects the inflammatory condition at the breast tumor site." (PMID 30934926, 2019). "In this study, we showed that SNAIL1 regulates expression of cytokines in primary breast tumor cells including IL-1α, IL-6, TNFα, and GM-CSF." (PMID 29593211, 2018). "In previous studies looking at correlations between TP and various immune mediators in the human breast tumour microenvironment, TP expression was associated significantly with expressions of TNF-α, IL-1α, and monocyte chemoattractant protein (MCP)-1." (PMID 15150550, 2004). "We analyzed the plasma and tumors for 32 cytokines/chemokines using a Discovery 32-plex Array and only found the following significant differences: Breast tumors from MMTV-PyVT mice latently infected with mCMV had a decreased expression of interleukin-1-alpha (IL-1α)." (PMID 30934926, 2019). "To further evaluate the clinical relevance of IL1α expression and macrophage infiltration in patients with TNBC, we used IHC staining to compare the levels of IL1α and CD163 between normal breast tissues and breast tumors." (PMID 37551997, 2023). "TNF-α expression and IL8, IL1A and IL6 expression were only correlated in ER-negative, but not in ER-positive breast tumors." (PMID 21754991, 2011).
inflammatory bowel disease (13 papers, 2013 to 2025). A spectrum of small and large bowel inflammatory diseases of unknown etiology. "In an in-vitro study, a significant reduction was seen in several inflammatory biomarkers including tumor TNF-α, IL-1α, IL-6, IL-8, T-cell interferon-gamma (IFN-γ), and IL-2, in the presence of ≥10 μg/ml garlic extract in inflammatory bowel disease." (PMID 30683061, 2019).
lupus (13 papers, 2006 to 2025). "In 2013, a meta-analysis was reported, investigating the genetic relationship between IL1A rs1800587 and rs17561 SNPs and the risk of systemic lupus erythematosus based on four case-control studies from three articles, which did not provide strong evidence for an association." (PMID 29879187, 2018). "Similar outcomes including IL-1α release and robust lung inflammation were noticed in silica-treated lupus-prone mice." (PMID 36840754, 2023). "For example, classical NF‐κB signalling knockout in lupus‐prone mice strongly down‐regulated levels of IL‐1α, IFN‐γ and IL‐6 in the kidneys." (PMID 33079487, 2020). "Though not all changes were statistically significant, similar observations were made for TNF-α, IL-1α, IL-6, and IL-18, which are known for their roles in inflammation and lupus development." (PMID 32413078, 2020). "Additionally, the levels of supernatant IL‐1α and IL‐1β, specific products of Caspase 11 activation, were also increased following incubation with lupus serum." (PMID 38881675, 2024). "Previously, the rs1800587 C/T SNP of IL1A gene was reported to not be linked to the risk or severity of systemic lupus erythematosus in a Spanish population, juvenile idiopathic arthritis in an Iranian population, and juvenile idiopathic arthritis in the UK." (PMID 29879187, 2018). "In addition to sterile inflammation induced by hypoxic or ischemic events, there is role for the IL-1α precursor in model of vascular inflammation such as the vasculitis of lupus." (PMID 24312098, 2013). "Together, common characteristics of lupus appear to be upregulation of members of the IL-1 family such as IL-1α and IL-1β and IL1R2, of the TNF/death receptor family such as TNF receptor II (TNFRSF1B), TRAIL (TNFSF10), and its decoy receptors, and a gene signature of IFN-α/β-regulated genes." (PMID 19884985, 2009). "Systemic lupus erythematosus (SLE)-like mouse models display endothelial dysfunction and cardiac hypertrophy, mediated through IL-6 and IL-1α." (PMID 33868242, 2021). "In addition, IL-1β−/− and IL-1α/β−/− mice are resistant to the induction of experimental lupus." (PMID 27250627, 2016). "The aim of this study was to evaluate the relevance of functional genetic variations of RANTES, IL-8, IL-1α, and MCP-1 for systemic lupus erythematosus." (PMID 16719905, 2006).
mastitis (13 papers, 2020 to 2025). Inflammation of breast tissue during lactation or postpartum due to an obstructed duct or infection. "IL-1α showed consistent expression across both bacterial challenges, suggesting its potential as a stable biomarker for mastitis susceptibility." (PMID 40453956, 2025). "In epithelial cells of bovine mammary glands, IL-1α effects were associated with the inflammatory response to induced mastitis." (PMID 35335696, 2022). "Interleukin-1 alpha (IL-1α) locally regulates first-line defense mediators in experimental acute bovine mastitis, including prostaglandin (PG-F2α) and leukotriene (LT-B4), indicating its participation in early inflammation." (PMID 40303387, 2025). "Studies have shown that in naturally occurring subclinical mastitis in cows, the intramammary inflammatory response is driven by IL–1α, IL–4, IL–12, IL–17A, and IFN–γ." (PMID 40005889, 2025). "Subclinical and clinical mastitis data demonstrate inflammatory responses to intramammary infection driven by IL-1α, IL-4, and IL-17A." (PMID 39195804, 2024). "TAC, Fb, ferritin, IL-1α, and IL-1β are valuable indicators for camel mastitis, but larger-scale studies on these markers are recommended." (PMID 37534071, 2023). "TNF-α and IL-6 are immunoreactive in cases of mastitis, while IL-1α of the IL-1 family is more capable of driving the corresponding inflammatory response." (PMID 37189805, 2023). "In both statuses of subclinical and clinical mastitis, IL-1α mean numbers (%) were statistically significantly lower than in healthy cows, suggesting its role in bovine mammary gland immunity and early inflammation." (PMID 35335696, 2022). "Studies evidence bovine mammary epithelial cells challenged with E. coli-derived lipopolysaccharides showed an increase in mRNA expression of IL-1α similar to that found in mastitis-affected cows." (PMID 35335696, 2022). "In experimental acute bovine mastitis, interleukin-1 alpha (IL-1α) demonstrates local modulation of such first-line defense mediators such as prostaglandin (PG-F2α) and leukotriene (LT-B4), suggesting its role in early inflammation." (PMID 35335696, 2022). "Data about subclinical and clinical mastitis demonstrate inflammatory responses to intramammary infection driven by IL-1α, IL-4, and IL-17A." (PMID 35335696, 2022). "The mean IL-1α immunoreactive cell count in healthy cows on day 4 was statistically significantly greater than in subclinical mastitis- (p = 0.012) and in clinical mastitis-affected cows (p = 0.004), but not on day 5 (p = 0.312) and day 6 (p = 0.107)." (PMID 35335696, 2022). "However, when further explored in a murine model for bovine mastitis, the enterobactin-deficient mutant vs. the wild-type strain revealed a significant reduction of the bacterial load and, consequently, a decrease in pro-inflammatory cytokines (IL-1α,−1β,−4,−6, and−8)." (PMID 33240956, 2020). "TAC, Fb, ferritin, IL-1α, and IL-1β are good biomarkers for camel mastitis." (PMID 37534071, 2023). "However, a peak in IL-1α immunoreactivity was noted on day 5 of clinical mastitis-affected cows suggesting its inflammatory role in the support and maintenance of inflammation." (PMID 35335696, 2022). "In terms of hub-hub genes, we identified several crucial immune and inflammatory response genes, including TLR2, TLR474, TNF, IL1β, IL1A, IL675, JAK276,77, and IL1068, which play important roles in the pathogen-host interactions during mastitis." (PMID 37620551, 2023). "The identification of IL-1α, IL-6, and CXCR1 as key modulators offers promising avenues for the development of molecular biomarkers and genetic selection strategies aimed at enhancing mastitis resistance in dairy herds." (PMID 40453956, 2025). "These preliminary data suggest that determination of IL-1α, MIP-1α, IL-4 in sheep milk samples could contribute to the diagnosis of subclinical mastitis." (PMID 41560862, 2025).
mastitis (continued). "Together, data about naturally occurring subclinical and clinical mastitis demonstrate inflammatory responses to intramammary infection driven by IL-1α, IL-4, IL-12, IL-17A, and IFN-γ in subclinical mastitis, and IL-1α, IL-4, IL-6, and IL-17A in clinical mastitis." (PMID 35335696, 2022). "On day 4 and 6, but not on day 5, mean IL-1α immunoreactive cell counts (%) of healthy animals almost doubled the values found in subclinical mastitis and clinical mastitis-affected animals." (PMID 35335696, 2022). "Thus, immunobiotic L. acidophilus CRL2074 capable of reducing the magnitude of leukocyte migration into the udder, which is reflected in the expression of IL-1α, IL-8, MCP-1, and CXCL3, might influence the clinical course of mastitis." (PMID 32466097, 2020).
tuberculosis (13 papers, 2013 to 2026). A chronic, recurrent infection caused by the bacterium Mycobacterium tuberculosis. "In a murine model of TB, IL-1α/β double knockout mice or mice deficient in IL-1R1 display increased susceptibility to M. tuberculosis infection." (PMID 29189980, 2018). "This was characterized by significantly elevated pro-inflammatory cytokines such as G-CSF, TNF-α, IL-1α, IL-1β, and IL-6, excessive neutrophil infiltration, and reduced pulmonary lymphocyte levels as tuberculosis (TB) progressed." (PMID 39178329, 2024). "Furthermore, the downregulation of Tnf, Mapk11, C3, Il1a, and Il1b in the tuberculosis and pertussis pathways reduces macrophages' ability to opsonize bacteria, perform phagocytosis, and initiate inflammatory responses." (PMID 40206211, 2025). "IL-1 family of cytokines, mainly IL-1α and IL-1β, are essential for resistance to tuberculosis." (PMID 36993821, 2023). "Therefore, we predicted central DEGs in the PPI network and noted strong interactions between TNF, IL-6, IL-10, IL-1β, CSF-2, IL-4, CXCL8, IFN-γ, IL-1α, and CXCL1, all of which are strongly associated with tuberculosis." (PMID 37818041, 2023). "In addition, it was confirmed that metformin increased proinflammatory cytokines (TNF-α, IL-1α, IL-1β, IL-6, IL-18, IL-8, and IFN-α) in Mycobacterium tuberculosis (causative agent of tuberculosis)-infected macrophages." (PMID 37700364, 2023). "Furthermore, Type I IFN inhibits host immune defense mechanism by negative regulation of IL-1α and IL-1β in tuberculosis." (PMID 31801478, 2019).
bladder cancer (12 papers, 1997 to 2025). "On one hand, EP300 loss-of-function relieves its inhibition on IL-1α signaling, activating the IL-6/JAK/STAT3 pathway and driving bladder cancer." (PMID 40375990, 2025). "Upon ELISA validation, urine IL-1α, IL-1ra, and IL-8 were able to distinguish control urine from urine drawn from various bladder cancer stages, with IL-8 being the best discriminator." (PMID 33889301, 2021). "We have here studied the expression of the cytokine interleukin-1α (IL-1α) in 73 human bladder carcinomas in relation to patient survival, and examined possible relationships between IL-1α and urokinase plasminogen activator (uPA) expression." (PMID 11161396, 2001). "The finding that urine IL-1α is elevated in BC is relatively novel since only one other study has noted that urine IL-1α may be induced following intravesical immunotherapy with BCG in noninvasive bladder cancer." (PMID 33889301, 2021). "We conclude that IL-1α is important for bladder cancer biology, and that measurements of this cytokine may be useful in pre-treatment characterization of urinary bladder cancer." (PMID 11161396, 2001). "An initial screen included a bladder cancer panel with 16 proteins (MCP‐1, MIP‐1α, MIP‐1β, IP‐10, IFN‐α, IL‐1α, IL‐1RA, IL‐8, IL‐7, IL‐31, IL‐15, TNF‐β, Eotaxin, SDF‐1α, Rantes, and GRO)." (PMID 38553868, 2024). "Using a human bladder carcinoma cell line, we observed that WT GBS induced significantly more transcription of interleukin (IL)-6, IL-8, and, to a lesser extent, IL-1α, than medium alone or the ΔcylE deletion mutant." (PMID 23505569, 2013). "Interestingly, it was shown that the proinflammatory cytokines IL1A and IL1B are most probably also related to bladder cancer invasion." (PMID 34070905, 2021). "These proteins may not effect proangiogenic pathways in bladder cancer; they can however interact with IL-1α, IL-8, VEGF (vascular-endothelial growth factor), and MMP-9 (matrix metalloproteinase-9) to enhance tumorigenesis and tumor invasiveness." (PMID 28929116, 2017).
disc degeneration (12 papers, 2009 to 2021). "IL1α, IL1β and IL1Ra and their composite genotype have previously been linked to disc degeneration and low back pain in the general population." (PMID 25207923, 2014). "Some polymorphisms of the IL-1α gene (IL1A) have been associated with disc degeneration." (PMID 25506053, 2014). "IL-1α was thought to be involved in the pathogenesis of disc degeneration by increasing the production of extracellular matrix degradation enzymes and by inhibiting extracellular matrix synthesis." (PMID 29884765, 2018). "Interleukin-1 α (IL-1α) was thought to be involved in the pathogenesis of disc degeneration by increasing the production of extracellular matrix degradation enzymes and by inhibiting extracellular matrix synthesis." (PMID 29884765, 2018). "IL-1α, produced mainly by activated macrophages, neutrophils, and epithelial and endothelial cells, is thought to be involved in the pathogenesis of disc degeneration by increasing the production of ECM degradation enzymes and by inhibiting ECM synthesis." (PMID 25506053, 2014). "During disc degeneration, it has been demonstrated that IVD cells secrete proinflammatory cytokines such as TNF‐α, IL‐1α, IL‐1β, IL‐6, and IL‐17." (PMID 31463438, 2018). "Intervertebral discs are known to respond to IL1A and IL1B in the multiple pathological processes of disc degeneration, such as inhibiting synthesis of the extracellular matrix and increasing synthesis of matrix metalloproteinases." (PMID 27253397, 2016).